TNRC6B (trinucleotide repeat containing adaptor 6B)
Diseases named in the same sentence as TNRC6B in open-access papers (continued):
Sharing a sentence is not in itself a finding about the gene and the disease.
tumor (9 papers, 2015 to 2023). "Like CDKN1B, TNRC6B was identified as one of the genes showing statistical evidence of positive selection for mutations in SI-NETs, suggesting a candidate tumor suppressor role for this gene in a subset of tumors." (PMID 35922826, 2022). "The most striking results were replicated associations of several variants in TNRC6B with either risk or tumor size." (PMID 26236334, 2015). "We also reported that the intronic variant rs138039 in TNRC6B is associated with tumor size in EA with a significance level close to the Bonferroni-corrected threshold of P = 0.0009 and that the lower MAF in AA likely precluded detection of the association." (PMID 26236334, 2015). "In addition to the previously reported CDKN1B loss-of-function mutations, we observed potential loss-of-function gene alterations in TNRC6B, a candidate tumor suppressor gene in a small subset of ileal NETs." (PMID 35922826, 2022). "The expression of circ‐TNRC6B in ESCC tissues was downregulated when compared with that in non‐tumor tissues." (PMID 37014625, 2023). "The expression of circ‐TNRC6B in ESCC tissues was markedly downregulated when compared to that in non‐tumor tissues." (PMID 37014625, 2023). "This study identified a novel tumor suppressor circRNA called circ‐TNRC6B, which was significantly downregulated in ESCC tissues." (PMID 37014625, 2023). "Clinical data analysis of tissue chip array suggested that the expression of circ‐TNRC6B in ESCC tissues was markedly downregulated when compared with that in non‐tumor tissues." (PMID 37014625, 2023). "This study identified a tumor suppressor circRNA derived from exons 9–13 of TNRC6B (circBase ID: hsa_circ_0063411) (called circ‐TNRC6B)." (PMID 37014625, 2023). "But if the relative expression of TNRC6B is > 5.618 and the relative expression of CDK6 is ≤ 2.841, patients can be classified as high-risk PCa, concretely, 2.4% of subjects can be correctly advanced the presence of an aggressive tumour." (PMID 37978493, 2023). "By doing so, we found a significant decrease in the expression of TNRC6B, AGO1, and CDK6 between the low-risk and high-risk groups, pointing to a decrease in the repressive machinery of microRNAs and proliferation in the aggressive tumours." (PMID 37978493, 2023). "The patient-based analysis identified one additional significant gene, ZNF845 (Padj = 2.6 × 10−2), whereas the tumor-based analysis identified four, TNRC6B (Padj = 2.9 × 10−4), ZNF780B (Padj = 4.2 × 10−2), RPP30 (Padj = 6.4 × 10−2), and CASQ1 (Padj = 8.7 × 10−2)." (PMID 35922826, 2022). "However, we corroborated the tumor-suppressive roles of insertions in Adk and Zbtb20 and in Nipbl, Pdlim5, Ppp1r12a, Tnrc6b, Brd4, Cul3, Ctnna3, Elavl1, Gphn, Nfia, Ptpn12, Taok3, and Rasa1." (PMID 33435458, 2021). "We next determined whether TNRC6B possessed tumor suppressive properties by evaluating its effect on cell proliferation." (PMID 28798471, 2017). "No variants that associated with risk also associate with tumor size; however, SNPs in TNRC6B other than those affecting risk influenced significantly (P = 0.001 at rs138039 and P = 0.008 at rs139909) tumor size in EA." (PMID 26236334, 2015). "Thus, circ‐TNRC6B may also exert tumor suppressive effects through other mechanisms, such as serving as protein scaffolds and transcription factors, interacting with RBPs, and encoding peptides or proteins, which warrant further investigations." (PMID 37014625, 2023). "Moreover, when we checked the expression of tumour lymph node involvement, N0 and N1, we observed a lower expression of TNRC6B in the N1 group, indicating that decrease expression may be related to tumour aggressivity." (PMID 37978493, 2023). "Second, while none of these studies reported evidence for TNRC6B rs139909 association with risk, association with tumor size (OR = 1.73; p = 0.008) was observed in the EA group in our study, potentially suggesting decreased power in the AA group that can be explained by the low MAF at this SNP." (PMID 26236334, 2015).
cancer (4 papers, 2021 to 2024). A tumor composed of atypical neoplastic, often pleomorphic cells that invade other tissues. "As a whole, the ETS1, TNRC6B, and TNRC6C genes were thought to be preventive against tumors, while the remaining SRGs appeared linked to cancer risk." (PMID 35911954, 2022). "Further investigation into AGO1, TNRC6B, NOVA1, MMP16, and their connection to miRNA processing could provide deeper insights into the molecular mechanisms underlying cancer recurrence." (PMID 39070144, 2024). "The connection with RNA processing factors, like TNRC6B and NOVA1, further underscores the multifaceted nature of miRNA-mediated regulatory networks in the context of cancer recurrence." (PMID 39070144, 2024). "It is noteworthy, however, that RNF128, SLC16A1, SPRED1, TNRC6B, and TTK are novel in that they are found only among the candidate cancer genes identified by forward genetic screens in mice or among the genes whose expression changes in cancer." (PMID 33427197, 2021).
neurodevelopmental disorder (3 papers, 2019 to 2026). A behavioral and cognitive disorder with onset during the developmental period that involves impaired or aberrant development of intellectual, motor, or social functions. "Our findings also underscore variable expressivity across generations and emphasise the relevance of both copy-number and sequence variants in TNRC6B in patients with neurodevelopmental disorders." (PMID 42074582, 2026). "Considering the miRNA and piRNA target genes common to multiple samples, four were already present in SFARI database: NACC1, SMAD4, TNRC6B, and TTN, and their mutants are implicated in ASD and other neurodevelopmental disorders." (PMID 35405953, 2022). "Interestingly, four of these LoF variants disrupted genes previously implicated in neurodevelopmental disorders: KAT6A (c.1599-56_1621del in proband 10), SETBP1 (c.1781del, p.P594Lfs*36 in proband 13), TNRC6B (c.2040G>A, p.W680* in proband 15) and ZFHX4 (c.3646-1G>A in proband 14)." (PMID 29463886, 2019). "A significant number of these genes (CHD3, SETD1A, KAT6A, SETBP1, TNRC6B, ZFHX4, ARID1A and TRIO) have been associated with neurodevelopmental disorders with or without speech problems." (PMID 29463886, 2019).
adenocarcinoma (1 paper, 2021). A common cancer characterized by the presence of malignant glandular cells. "Of note, SNVs shared between the DMBA-induced organoid-derived adenocarcinomas and 0.6 μM DMBA-treated organoids (prior to injection into the subcutis of nude mice) were limited to 10 genes, including Tnrc6b and Vps13d, which were selected by the IGV." (PMID 34912374, 2021).
infection (1 paper, 2024). The state of being infected such as from the introduction of a foreign agent such as serum, vaccine, antigenic substance or organism. "On the other hand, six targets produced positive Z-scores (>1.96) that indicated increased infection upon CRISPR targeting: RANBP2-like and GRIP domain containing 2 and 4 (RGPD2 and RGPD4), trinucleotide repeat containing adaptor 6B (TNRC6B), FAM21C, KIA00196 (aka, strumpellin), and zyxin." (PMID 38953638, 2024).
TNRC6B also shares sentences with these, for which no sentence is quoted: Intellectual disability (3 papers); Uterine leiomyoma (2); acute myeloid leukemia (1); adult T-cell leukemia (1); Alzheimer disease (1); amblyopia (1); attention deficit and hyperactivity disorder (1); behavioral disorders (1); craniosynostosis (1); digestive system neoplasm (1); generalized epilepsy (1); hearing loss (1); lipoma (1); liver disease (1); lung adenocarcinoma (1); lymphoma (1); maturity-onset diabetes of the young (1); mental disorder (1); metastatic prostate carcinoma (1); Obesity (1); Pheochromocytoma and Paraganglioma (1); rheumatoid arthritis (1); Strabismus (1); tauopathy (1).